CD28 (CD28 molecule)
Diseases named in the same sentence as CD28 in open-access papers (continued):
Sharing a sentence is not in itself a finding about the gene and the disease.
infection (continued). "Interestingly, abrogation of CD28 costimulation in CD28−/loxCre+/− mice by oral administration of tamoxifen prior to secondary infection with N. brasiliensis resulted in impaired worm expulsion, similarly to infected CD28−/− mice." (PMID 24516382, 2014). "Consequently, CD28-deficient mice have reduced expansion of effector CD4+ T cells and do not form T helper type 1 (Th1) and T follicular helper (Tfh) cells after infection or immunization." (PMID 25347065, 2014). "Importantly, interfering with CD28 costimulatory signalling before re-infection impaired the recruitment and/or expansion of central and effector memory CD4+ T cells and follicular B cells to the draining lymph node of tamoxifen treated CD28−/loxCre+/− mice." (PMID 24516382, 2014). "Loss of CD28 after T cell activation impairs the Th1 response over the course of an infection because at day 12, but not at day 5, post infection there are fewer Th1 cells in Cd28flox/floxOx40cre/+ mice compared with controls." (PMID 25347065, 2014). "Furthermore, infection of CD28−/− mice with the fungi B. dermatitidis showed that development of memory responses is CD28 independent." (PMID 24516382, 2014). "Cd28flox/floxOx40cre/+ mice had comparable levels of Influenza M1 viral RNA in their lungs compared with heterozygous control mice at 7 days post infection, suggesting that the loss of CD28 on effector CD4+ T cells does not impair viral clearance." (PMID 25347065, 2014). "Likewise, Vitelli-Avelar reported decreased levels of CD62L+CD4+ T cells but lower frequencies of CD4+HLA-DR+ T cells along with unaltered levels of CD4+CD28+ T cells in children in the indeterminate phase of the infection." (PMID 24349591, 2013). "Notably, the frequency of CD27+CD28- cells predominated the HIV-specific CD8+ T cell subset throughout infection, and very few cells transitioned to lose CD27 expression by 23–24 months (mean 3.9%, range 1.1–6.1%)." (PMID 21655252, 2011). "Primary CD4+ T cells were activated with CD3 and CD28 mAbs for 24 hours before infection with HIV." (PMID 21698207, 2011). "Furthermore, we observed that robust CD3 and CD28 downregulation led to low levels of T cell activation, consistent with a non-pathogenic infection." (PMID 41329000, 2025). "The weak microglial activation in the early phase of TMEV-infection in both types of CD28-knockout mice indicates a disruption of an activation pathway, which could not be quickly overcome by other routes of co-stimulation and is somewhat independent of the B- and T cell infiltration." (PMID 37090733, 2023). "In addition, it has been demonstrated that expression of CD28 on the surface of T cells is significantly decreased in patients with severe infection, and the reduction of CD28 expression may be an important risk factor for high mortality." (PMID 36106958, 2022). "We first compared virus-specific CD8+ T cells in early and late chronic LCMV clone 13 (cl13) infection and noted that exhausted GP33-specific CD8+ T cells share a similar senescence-associated mRNA expression pattern when compared to dysfunctional human CD3/CD28 stimulated CD8+ T cells." (PMID 34434190, 2021). "Finally, the ability of Vpu to downregulate CD28 is conserved between multiple group M Vpu proteins and infection with viruses encoding or lacking Nef and Vpu have differential effects on activation upon stimulation." (PMID 29329537, 2018). "Moreover, we hypothesized that the function of CD28 downregulation is relevant during infection and that CD28 downregulation by Nef and Vpu may alter cell activation through CD28 receptor stimulation." (PMID 29329537, 2018). "Next, considering that (i) CD28- cells exhibit replicative exhaustion, and (ii) p16INK4a, a biomarker of replicative senescence, accumulates in cells undergoing replicative exhaustion during inflammation/infection, the average amount of p16INK4a per T-PBL (judging by MFI) was determined." (PMID 30086167, 2018).
infection (continued). "For instance, B7 molecules are expressed on dendritic cells and macrophages in lymphoid tissue, the levels of which are upregulated during infection and inflammation; their inappropriate binding to and stimulation of CD28 could have adverse pathological consequences." (PMID 30564247, 2018). "Furthermore, during infection, persistent T cell activation drives proliferation that results in the accumulation of senescent, antigen-experienced memory T cells with reduced expression of CD28 and increased expression of CD57." (PMID 27231509, 2016). "Thus, requirement of CD28 downstream signaling for Tfh generation may be infection specific, and still there is scope to determine unknown CD28 downstream signaling molecules." (PMID 27933060, 2016). "CD4+ T-cells were then infected with HVS at a multiplicity of infection (MOI) of 0.5 and activated in a flask coated with anti-CD3/anti-CD28 antibodies for three days." (PMID 41596728, 2026). "Overall, the ability of SIV Nef to modulate T cell activation by downregulating CD3 and CD28 is consistent with a non-pathogenic phenotype, while retaining these receptors on the T cell surface leads to increased T cell activation and inflammation, consistent with a pathogenic infection." (PMID 41329000, 2025). "In both CD28-knockout strains, microglial activation and change of morphology as reaction to the acute TMEV-infection in the brain were reduced." (PMID 37090733, 2023). "During primary infection, CMV-specific CD8+ T cells exhibit an antigen-driven early-differentiating phenotype (CD27+CD28+ CD45RO+CD45RA−) armed for cytotoxicity." (PMID 38020746, 2023). "The dynamics and interaction between CD4+CD25+ and co-stimulatory molecules such as CD28, CD80, CD40 and CD40LG during infection with A. phagocytophilum in sheep needs further investigation in the future." (PMID 37989861, 2023). "After a primary infection in SOT recipients, CMV-specific CD4+ T cells can be detected 1 week after the occurrence of CMV DNAemia, more specifically those CD4+ CD28-granzyme B+ cells." (PMID 38020746, 2023). "While CD28 Ab, VCAM-1 and MAdCAM-1 all promoted the formation of TRM-like cells, only MAdCAM-1 + RA costimulation consistently supported infection." (PMID 36897929, 2023). "Our results show that both UL40-sepcific and pp65-specific responses belong to TEMRA cells after a primary infection and display a stable CD27-/CD28-, CCR7-, CD45RA+, CD8+ TEMRA phenotype which persist lifelong in HCMV+ healthy hosts." (PMID 36532017, 2022). "TNF receptor-associated factor 3 (TRAF3) was shown to be recruited in the TCR/CD28 signalling complex in murine CD4+ T cells and critical for T cell-mediated immunity to infection." (PMID 35142878, 2022). "CD40L−/− mice exhibited exacerbation of infection with a high fungal burden due to diminished interferon-γ production by CD4 and CD8 cells and decreased CD28 expression by CD4 cells." (PMID 35425769, 2022). "Following infection, frequencies of both central memory (CD95+ CD28-) CD4+ and CD8+ T cells increased while effector memory (CD95+ CD28-) frequencies declined indicative of antigen driven activation and migration of T cells." (PMID 34494025, 2021). "To characterize the state of differentiation of CAR-transduced T lymphocytes in the post-infection period and during antigenic restimulation, we cytometrically analyzed the expression of different surface markers, namely CD62L, CD27, CD28, CCR7, and CD57." (PMID 34660275, 2021). "We observed that RhCMV-specific CTLs were overwhelmingly (>90%) TEM2 (CD28– CCR7–), both before and during SIVmac239 infection." (PMID 32922404, 2020). "major infection were restimulated with anti-CD3 and anti-CD28 for 4 h in brefeldin A, followed by intracellular staining for Th1 and Th2 cytokines." (PMID 32948646, 2020). "CD28 and ICOS, co-stimulatory receptors important for signaling through the TCR, were both downregulated by infection." (PMID 32452381, 2020).
infection (continued). "Unfortunately, but not unexpectedly given the size of the Cas9 gene, retroviral transduction of anti-CD3/anti-CD28 stimulated cultured mouse CD4+ T cells resulted in very low (∼5%) transduction rates, as indicated by GFP expression 48 h after infection." (PMID 29436394, 2018). "Primary CD4+ T cells were activated with αCD3/CD28 beads + 20 U/mL IL-2 for 3 days before infection with different amounts of HIVGKO (input, ng/p24) and analyzed by flow cytometry 4 days post-infection." (PMID 29714165, 2018). "Infection of cells activated through the T cell receptor, using anti-CD3/CD28 conjugated beads, was similarly enhanced by eSF co-culture." (PMID 28207890, 2017). "In the late stage of infection, or (in our study) long after vaccination, YF-tetramer+CD8+ T-cells for instance have a heterogeneous expression of CD28 and have re-expressed CD45RA, as is seen in CMV-specific late stage effector cells." (PMID 26977808, 2016). "After anti-CD3/CD28 mAb stimulation, TIM3+PD1– T cells produced more IFNγ and TNF than other T cells even late during infection." (PMID 26967901, 2016). "In contrast, even before infection, a large proportion of RSV-specific CD8+ T cells had already downregulated CD28 and CD27+CD28+ double-positive cells were in the minority." (PMID 26687547, 2015). "For example, CD28, a protein known to decrease apoptosis of T lymphocytes and to increase migration of memory T cells was down-regulated after YFV-DakH1279 infection whereas, RASSF4, a gene believed to be involved in apoptosis, was up-regulated." (PMID 25412185, 2014). "This demonstrates that CD28 signaling is required for the initiation of the CD4+ memory T cell response, in addition to being required throughout the primary immune response to infection." (PMID 25347065, 2014). "We found that Tregs did express high levels of both CD28 and CTLA4, as well as lower levels of CD86 over the course of infection." (PMID 25144228, 2014). "Together, these data suggest that CD28 is essential for the expansion of central and effector memory CD4+ T cells during re-infection with N. brasiliensis." (PMID 24516382, 2014). "CD28 expression was upregulated from 4 to 12 weeks and CXCR3 expression was upregulated at 8 and 12 weeks post-infection." (PMID 23448601, 2013). "The frequency (0.088–3.9% of CD3+CD8+ cells) and phenotype (CD27+CD28−, CD45RA+/−, CD57+/−, HLA-DR+, CD95+) of infant HIV-specific CD8+ T cells were similar to reports in adults undergoing early infection." (PMID 21655252, 2011). "In order to assess Th1 differentiation ex vivo, we purified CD4 T cells from spleens 10 days after infection and restimulated them with plate-bound antibodies against CD3 or a combination of CD3 and CD28 at different concentrations." (PMID 20668698, 2010). "In CD3/CD28 pre-activated CD4 T cells, both the VSV-G-pseudotyped HIV-1 and the wild-type virus replicated after infection (Figure 5A1 and 5B1)." (PMID 19851458, 2009). "Age > 60, a clinical factor associated with the TLT subtype, was associated with 57 upregulated genes, including BCR signaling genes, IL6 (related to infection), and IL21R (different from TLT vs. ME), and 141 downregulated genes including EPCAM, AR, WT1, and CD28." (PMID 39866884, 2025). "Epigenetic processes are central to T cell lineage decisions but most studies have focussed on the impact of histone modifications in disease and infection models and DNA methylation studies of CD8+ T cell activation using CD3/CD28 stimulation models have been conducted primarily in mice." (PMID 38899429, 2024). "Using high-parameter flow cytometry, we evaluated these features in CD4+ T cells from rs6861(TT) versus rs6861(CC) genotyped HIV-1-infected individuals during the chronic stages of infection at steady-state and upon activation with an HIV-1 peptide-pool or soluble anti-CD3 and anti-CD28." (PMID 38548722, 2024).
infection (continued). "CD28 is critical for T cell proliferation and survival, cytokine production, and CD4+ T cell activation, and its persistent expression is necessary for CD4+ T cell polarization in response to infection." (PMID 38982223, 2024). "Cluster 3, which identified genes upregulated at day 7 post-infection, was highly enriched for T cell responsive genes, including those involved in T cell activation, lymphocyte proliferation, and TCR signaling, e.g. CD3D/E/G, CD8A/B, CD28, CD40LG, and GATA3." (PMID 38950078, 2024). "The percentage of CD28+CD95+ central memory CD4+ T cells (CD4+ Tcm) showed no significant change during infection, implying that naive CD4+ T cells differentiated into effector CD4+ T cells." (PMID 37033979, 2023). "It is noteworthy that, while CD28 is a costimulatory receptor expressed on activated T cells, CD44 is an adhesion receptor involved in activated T cell migration between lymphoid tissues and sites of infection." (PMID 37896880, 2023). "Cytotoxic T cells lacking CD28 generate similar numbers of viral specific cells at the height of infection, but fail to maintain equivalent numbers during the memory phase." (PMID 38127070, 2023). "Consequently, during infection or inflammation, APCs upregulate CD86 and CD80 and both signals, TCR and CD28, are activated, so that T-cells perform target killing, with long-term persistence." (PMID 34771581, 2021). "CD28-deficient mice have increased IFN-γ, which is important for limiting Pneumocystis-associated inflammation, but not in the resolution of infection." (PMID 33669726, 2021). "Immunophenotyping tests showed that infection by Pic-producing bacteria did not alter the total number of lymphocytes from the spleen, but the number of helper T cells expressing CD28 was higher in the mutant than other groups." (PMID 32197297, 2020). "At different time points of infection, single lung cell suspensions were prepared, and intracellular staining of IFNγ in CD4+ T cells was performed after 4 hrs of incubation in medium or after restimulation with anti-CD3/CD28." (PMID 33375150, 2020). "After infection, MP antigen may activate CD8+ T cells through TCR; upregulated RLTPR and CARD11 genes may co-stimulate CD8+ T cells through CD28." (PMID 29967623, 2018). "To determine the responsiveness of T cell in T. spiralis-infected mice, we examined the CD4+ T cell proliferation upon non-specific (anti-CD3/anti-CD28) and antigen-specific stimulation in WT and PD-1−/− mice with or without infection." (PMID 30093899, 2018). "Infection of AGM PBMCs confirmed that viral constructs expressing the parental SIVagm Nef (WT, GU) and the HIV-1 Nef (1N, GU1N) differed markedly in their CD3 downmodulation function, while all SIVagm constructs were capable of downmodulating MHC-I and CD28." (PMID 29636452, 2018). "A previous study has shown that CD28−/− BALB/c mice infected with Toxoplasma gondii (T. gondii) developed a T-cell response that was sufficient to provide resistance to the infection, suggesting that the ICOS receptor is an excellent candidate for inducing a CD28-independent activation of T cells." (PMID 30405039, 2018). "Finally, similar to eSF-mediated enhancement of NLENG1I, eSF enhanced BaLGFP and THROGFP infection of purified CD4+ T cells, and efficient enhancement was observed with T cells activated through either PHA/IL2- or anti-CD3/CD28." (PMID 28207890, 2017). "CD28 signaling positively regulates early stage of Tfh differentiation (expression of ICOS and BCL-6), and its signaling is also important at late stage of Tfh differentiation as exemplified in blocking B7 ligand during ongoing infection impaired Tfh response." (PMID 27933060, 2016). "Most infections were carried out in the presence of PHA and IL-2 stimulation, although stimulation with anti-CD3, anti-CD28 mabs resulted in similar levels of infection (not shown)." (PMID 26055104, 2015).
infection (continued). "CD28−/− mice and mice given tamoxifen prior to secondary infection failed to expel adult N. brasiliensis worms." (PMID 24516382, 2014). "Studies suggest that CD28 is not required during recall of memory T cell responses to infection with N. brasiliensis and H. polygyrus." (PMID 24516382, 2014). "Next, we infected CD3/CD28 stimulated CD4+ T-cells with wt JR-CSF, S142N or the K421D Env pseudotyped virus, and assessed the infection of the indicated CD4+ T-cell subsets via intracellular p24 staining and multiparametric FACS analysis three days post-infection." (PMID 24957778, 2014). "In contrast, infection of CD28−/− mice with H. polygyrus did not hamper normal development of Th2 immune response." (PMID 24516382, 2014). "In fact, infection with H. polygyrus seems to be sufficient to induce polyclonal antibody responses even in the absence of CD28 costimulation, supporting the suggestion that parasites can trigger polyclonal B cells responses." (PMID 24516382, 2014). "Together, these data suggest that cellular interactions between CD4+ T cells expressing CD28 and CD19+B220+ B cells are required for the expansion and/or recruitment of follicular B cells into the lymphoid tissue during N. brasiliensis secondary infection." (PMID 24516382, 2014). "In mice given large challenge doses of MAC, suppressor macrophages were generated in the spleen of host mice during weeks 2 to 3 after infection, followed by subsequent reduction of the responsiveness of splenic T cells to Con A stimulation and TCR signaling induced by anti-CD3/anti-CD28 antibodies." (PMID 22666284, 2012). "Among untreated persons at this early infection time-point with high CD8+ T cell activation levels, we observed a greater fraction of both total and HIV-1 gag specific CD8+ T cells fall into the intermediate memory (CD27+CD28−) phenotype." (PMID 19198651, 2009). "The number of these cells increase early on and throughout the course of infection, suggesting that the CD8+CD28- T-cells may be involved in the control of virus replication." (PMID 18923697, 2008). "Notably, this T cell-specific lentiviral vector does not require additional anti-CD3/CD28 stimulation for primary T cell activation during infection in vitro." (PMID 41844687, 2026). "For example, in the context of acute severe infection, we might expect a greater degree of upregulation of glycolysis in certain T cell subsets than was possible to achieve via our protocol with 2 h of activation with a CD3/CD28 agonist." (PMID 39906176, 2025). "Mice with a conventional CD28-knockout (CD28KO) either showed no clinical signs, similar to the control animals (B6-nT) or developed motoric deficiencies at 21 (n=1), 32 (n=1) and 33 (n=2) days post TMEV-infection." (PMID 37090733, 2023). "In summary, the absence of CD28 in T cells severely impacts the immune response against Theiler`s murine encephalomyelitis virus (TMEV)-infection, but significant differences are also seen depending on the time point of the deletion during the development of the immune system." (PMID 37090733, 2023). "Since T cells have been implicated in CS and CD28, CTLA4, and PD-L1 influence both innate and adaptive immune responses to infection, we asked whether the absence of CD28, CTLA4, or PD-L1 would affect the progression of CS in ocularly infected mice." (PMID 34281386, 2021). "Latent subclinical infection caused by CMV may lead to immunological alterations linked to aging, such as the accumulation of memory CD8+ cells that do not express CD28." (PMID 33777045, 2021). "Additionally, retro-miR-150 infection of mir-150−/− CD8+ T cells reduced expression of anergy-related genes Cbl-b, Egr2, and p27 and increased the expression of activation-induced molecules granzyme B, cyclin B1, and Blimp1 following anti-CD3/CD28 stimulation." (PMID 28572627, 2017). "Thus, in various infections but not during LCMV infection the CD28/B7 costimulatory pathway is highly critical in driving T cell expansion." (PMID 26263500, 2015).